OSBP2 (oxysterol binding protein 2)
Description:
Mediates the bidirectional lipid exchange between intracellular compartments and the plasma membrane, delivering cholesterol to the plasma membrane while transferring PI(4,5)P(2) to internal organelles, thereby modulating membrane lipid composition and associated signaling pathways. Binds 7-ketocholesterol. Acts during spermatid development where its function is required prior to the removal of cytoplasm from the sperm head (By similarity).
Synonyms: ORP2; ORP-4; KIAA1664; ORP4; OSBPL4; HLM; OSBPL1
Tractability: Small molecule: a high-quality ligand is known. Antibody: UniProt places it where antibodies can reach, with high confidence; its Gene Ontology location is reachable by antibodies, with medium confidence. PROTAC: ubiquitination databases record sites on it; a small molecule that binds it is known.
Gene: Protein-coding gene on chromosome 22 (30,693,782 to 30,907,824, forward strand). Ensembl gene ENSG00000184792.
Subcellular location: Membrane; Cytoplasmic vesicle, secretory vesicle, acrosome
Subcellular location (Human Protein Atlas): Cytosol
Gene Ontology:
Molecular function: cholesterol binding; protein binding; lipid binding; small molecule binding; sterol binding
Biological process: spermatid development
Cellular component: membrane; acrosomal vesicle; cytosol; perinuclear endoplasmic reticulum; plasma membrane; apical dendrite
Genetic constraint (gnomAD): Loss-of-function variants: 64 observed, 88.22 expected, observed/expected ratio (o/e) 0.73, 90% interval 0.59 to 0.89. The upper end of that interval is the gene's LOEUF score, 0.89, which puts it in group 3 of 6, group 1 being the genes least tolerant of losing a copy. Missense variants: 1,002 observed, 1,168.8 expected, observed/expected ratio (o/e) 0.86, 90% interval 0.81 to 0.9. Synonymous variants: 487 observed, 498.34 expected, observed/expected ratio (o/e) 0.98, 90% interval 0.91 to 1.05.
Homologues: Orthologues: chimpanzee OSBP2 (99% identical), macaque OSBP2 (95% identical), rabbit OSBP2 (86% identical), rat Osbp2 (84% identical), mouse Osbp2 (82% identical), pig OSBP2 (68% identical), dog OSBP2 (64% identical), zebrafish osbp2b (60% identical), guinea pig Osbp2 (14% identical). Paralogues in human: OSBP (51% identical), OSBPL6 (26% identical), OSBPL1A (25% identical), OSBPL3 (25% identical), OSBPL7 (23% identical), OSBPL2 (18% identical), OSBPL5 (17% identical), OSBPL8 (17% identical), OSBPL10 (15% identical), OSBPL11 (15% identical), OSBPL9 (15% identical).
Diseases named in the same sentence as OSBP2 in open-access papers:
OSBP2 is named in the same sentence as 21 diseases in open-access papers, as found by Europe PMC text mining. Sharing a sentence is not in itself a finding about the gene and the disease. The quoted sentences say what the papers report.
teratozoospermia (4 papers, 2016 to 2020). "OSBP2 has been reported to be essential for the post-meiotic differentiation of germ cells, while the lack of OSBP2 (ORP4) caused male infertility owing to oligo-astheno-teratozoospermia." (PMID 31333723, 2019). "In previous studies, oxysterol-binding protein 2 (OSBP2) has been elucidated playing an important role in the postmeiotic differentiation of germ cells and would cause male infertility owing to oligo-astheno-teratozoospermia with lack of OSBP2 (ORP4)." (PMID 33093844, 2020).
male infertility (3 papers, 2019 to 2024). The inability of the male to effect fertilization of an ovum after a specified period of unprotected intercourse. "Deficiency of Osbp2 has been shown to cause male infertility with a corresponding severe OAT phenotype in mice." (PMID 38509755, 2024).
breast carcinoma (2 papers, 2020 to 2022). "Members of this family are frequently de-regulated in cancer, including ORP5 in pancreatic cancer and lung cancer, ORP7 in breast cancer, and OSBP2 in cholangiocarcinoma." (PMID 32098402, 2020).
hepatocellular carcinoma (2 papers, 2018 to 2023). A malignant tumor that arises from hepatocytes. "Our results also demonstrate that the gene OSBP2 functions in cell proliferation, while SAMSN1 is associated with the malignant hepatocellular carcinoma phenotype." (PMID 29187421, 2018).
leukemia (2 papers, 2025). A malignant (clonal) hematologic disorder, involving hematopoietic stem cells and characterized by the presence of primitive or atypical myeloid or lymphoid cells in the bone marrow and the blood. "To validate these pooled screening results in an arrayed format in the context of leukemia, we conducted a CRISPR-based dropout experiment in KBM7 and Jurkat cells by inducing either single or dual OSBP/OSBP2 knockout(s)." (PMID 38907113, 2025).
pancreatic cancer (2 papers, 2020 to 2021). "Relationship between the expression level of OSbp2 and the clinicopathological parameters of pancreatic cancer patients." (PMID 35127474, 2021). "Here, we provided relevant evidence indicating that OSBP2 is a hallmark of malignancy, offered strong data showing that it regulates EMT through novel mechanisms and highlighted its potential as a marker for stratifying pancreatic cancer patient." (PMID 35127474, 2021). "However, there were no data in the literature describing OSBP2 expression and function in pancreatic cancer." (PMID 35127474, 2021).
pancreatic ductal adenocarcinoma (2 papers, 2021 to 2023). An infiltrating adenocarcinoma that arises from the epithelial cells of the pancreas. "Oxysterol-binding protein 2 (OSBP2) is crucial for promoting the growth and development of cancers; however, its effects on pancreatic ductal adenocarcinoma (PDAC) are still unclear." (PMID 35127474, 2021).
lymph node metastasis (1 paper, 2021). "Our data demonstrated that OSBP2 expression in PDAC tissues were related to nerve invasion (P <0.05) and pathological grading (P <0.05) but were not related to age, sex, lymph node metastasis or AJCC stage." (PMID 35127474, 2021).
cancer (10 papers, 2020 to 2025). A tumor composed of atypical neoplastic, often pleomorphic cells that invade other tissues. "Intriguingly, despite this, a comparison between the sensitivities of various cancer cell lines to orpinolide and the mRNA expression levels of OSBP or ORP4-encoding OSBP2 did not reveal significant correlations." (PMID 38907113, 2025).
tumor (3 papers, 2021 to 2023). "Here, we report that OSBP2 is an efficient tumor-associated protein to lead to extremely malignant characteristics in PDAC." (PMID 35127474, 2021). "This study is the first to demonstrate that OSBP2 may work as a tumor-associated protein that significantly affects the malignant behaviors of PDAC." (PMID 35127474, 2021). "By contrast, OSBP2 overexpression dramatically decreased the number of apoptotic cells and increased the number of tumor cells compared with those of empty vector-treated BXPC-3 cells." (PMID 35127474, 2021). "OSBP2 inhibition significantly increased the number of apoptotic cells and decreased the number of tumor cells compared with those of the control ASPC-1 cells." (PMID 35127474, 2021). "We examined the effect of OSBP2 on tumor growth using transplanted tumor mouse models." (PMID 35127474, 2021). "To verify the role of NR6A1, OSBP2 and UNC119B in HCC progression, we analyzed the correlation between gene expression and HCC tumor size, pathological grade and clinical stage according to TCGA database." (PMID 37903971, 2023). "High expression of OSBP2 and UNC119B was related to advanced tumor stage of HCC." (PMID 37903971, 2023). "The expression of OSBP2 in PDAC tissues was obviously higher than that in paracarcinoma tissues; more importantly, patients with high OSBP2 expression had a worse prognosis, which suggests that OSBP2 could serve as a potential tumor marker for PDAC patients." (PMID 35127474, 2021).
OSBP2 also shares sentences with these, for which no sentence is quoted: acute lymphoblastic leukemia (2 papers); lung carcinoma (2); ovarian carcinoma (2); T-cell acute lymphoblastic leukemia (2); age-related macular degeneration (1); cholangiocarcinoma (1); infection (1); kidney diseases (1); liver cancer (1); multiple myeloma (1); sterility (1).